GGT3P (gamma-glutamyltransferase 3 pseudogene)
Description:
Hydrolyzes and transfers gamma-glutamyl moieties from glutathione and other gamma-glutamyl compounds to acceptors.
Synonyms: GGT3
Gene: Transcribed unprocessed pseudogene on chromosome 22 (18,773,825 to 18,791,223, reverse strand). Ensembl gene ENSG00000197421.
Subcellular location: Membrane
Diseases named in the same sentence as GGT3P in open-access papers:
GGT3P is named in the same sentence as 3 diseases in open-access papers, as found by Europe PMC text mining. Sharing a sentence is not in itself a finding about the gene and the disease.
GGT3P shares sentences with these, for which no sentence is quoted: epistaxis (1 paper); infection (1); Wolf-Hirschhorn syndrome (1).